RNU7-97P (RNA, U7 small nuclear 97 pseudogene)
Gene: Small nuclear RNA gene on chromosome 17 (42,440,198 to 42,440,259, reverse strand). Ensembl gene ENSG00000238704.
Homologues: Orthologues: chimpanzee U7 (98% identical), macaque U7 (82% identical). Paralogues in human: RNU7-174P (85% identical), RNU7-111P (84% identical), RNU7-124P (84% identical), RNU7-130P (84% identical), RNU7-28P (84% identical), RNU7-35P (84% identical), RNU7-40P (84% identical), RNU7-60P (84% identical), RNU7-7P (84% identical), RNU7-113P (82% identical), RNU7-11P (82% identical), RNU7-120P (82% identical), and 141 more.